CACNB4 (calcium voltage-gated channel auxiliary subunit beta 4)
Description:
The beta subunit of voltage-dependent calcium channels contributes to the function of the calcium channel by increasing peak calcium current, shifting the voltage dependencies of activation and inactivation, modulating G protein inhibition and controlling the alpha-1 subunit membrane targeting.
Synonyms: CAB4; CACNLB4; EJM4; EA5; EIG9; EJM; EJM6
Tractability: Small molecule: an approved drug acts on it; a high-quality ligand is known; it belongs to a druggable protein family. Antibody: its Gene Ontology location is reachable by antibodies, with high confidence. PROTAC: its protein half-life has been measured.
Gene: Protein-coding gene on chromosome 2 (151,832,771 to 152,099,167, reverse strand). Ensembl gene ENSG00000182389.
Pathways (Reactome):
Developmental Biology: NCAM1 interactions
Neuronal System: Presynaptic depolarization and calcium channel opening
Gene Ontology:
Molecular function: calcium channel regulator activity; protein binding; voltage-gated calcium channel activity; high voltage-gated calcium channel activity; protein kinase binding; voltage-gated calcium channel activity involved in regulation of presynaptic cytosolic calcium levels
Biological process: calcium ion transmembrane transport; calcium ion transport; chemical synaptic transmission; positive regulation of muscle contraction; negative regulation of cell population proliferation; negative regulation of G1/S transition of mitotic cell cycle; positive regulation of protein localization to nucleolus; regulation of presynaptic cytosolic calcium ion concentration; regulation of synaptic vesicle exocytosis
Cellular component: voltage-gated calcium channel complex; cytoplasmic side of plasma membrane; cytosol; L-type voltage-gated calcium channel complex; T-tubule; glutamatergic synapse; nuclear speck; presynapse; synapse
Genetic constraint (gnomAD): Loss-of-function variants: 20 observed, 37.36 expected, observed/expected ratio (o/e) 0.54, 90% interval 0.38 to 0.78. The upper end of that interval is the gene's LOEUF score, 0.78, which puts it in group 3 of 6, group 1 being the genes least tolerant of losing a copy. Missense variants: 303 observed, 410.36 expected, observed/expected ratio (o/e) 0.74, 90% interval 0.67 to 0.81. Synonymous variants: 152 observed, 158.99 expected, observed/expected ratio (o/e) 0.96, 90% interval 0.84 to 1.09.
Gene-disease validity (ClinGen):
ClinGen rates the evidence that CACNB4 causes each of these diseases.
epilepsy (autosomal dominant): Refuted. A brain disorder characterized by episodes of abnormally increased neuronal discharge resulting in transient episodes of sensory or motor neurological dysfunction, or psychic dysfunction.
Homologues: Orthologues: chimpanzee CACNB4 (100% identical), macaque CACNB4 (100% identical), guinea pig CACNB4 (99% identical), pig CACNB4 (99% identical), rat Cacnb4 (98% identical), dog CACNB4 (97% identical), tropical clawed frog cacnb4 (93% identical), mouse Cacnb4 (90% identical), zebrafish cacnb4a (87% identical), Drosophila melanogaster Ca-beta (58% identical), Caenorhabditis elegans ccb-1 (52% identical), Caenorhabditis elegans ccb-2 (22% identical). Paralogues in human: CACNB2 (68% identical), CACNB1 (63% identical), CACNB3 (62% identical).
Diseases named in the same sentence as CACNB4 in open-access papers:
CACNB4 is named in the same sentence as 47 diseases in open-access papers, as found by Europe PMC text mining. Sharing a sentence is not in itself a finding about the gene and the disease. The quoted sentences say what the papers report.
epilepsy (14 papers, 2007 to 2026). "Heterozygous CACNB4 variants have been implicated in epilepsy and episodic ataxia, and the Cacnb4 knockout mice have a severe neurological phenotype." (PMID 32176688, 2020). "EA5 (MIM601949) was identified when a series of families with episodic ataxia and epilepsy harboured mutations in the calcium channel b4 subunit CACNB4, on chromosome 2q22-23." (PMID 22379397, 2011). "The role of voltage-gated channels in the activity of neuronal excitability indicates that mutations in Ca2+ channel genes CACNA1A, CACNA1H, CACNA2D2, and CACNB4 might be associated with the occurrence of epilepsy." (PMID 38383918, 2024). "Other CACNB4 mutations have been associated with epilepsies." (PMID 37008993, 2023). "DNA of the proband’s father was not available since he passed away prior to the analysis, therefore WES was performed only on the girl’s DNA and identified two heterozygous variants in two different epilepsy-associated genes, CACNB4 (NM_000726.5) and ZEB2 (NM_014795.4)." (PMID 36360260, 2022). "For example, EA and epilepsy associations include EA1 (KCNA1), EA2 (CACNA1A), EA5 (CACNB4), EA6 (SLC1A3), SCN2A, KCNA2, ATP1A3, SLC2A1, and PRRT2." (PMID 37008993, 2023). "Epilepsy and ataxia were also reported due to the heterozygous mutation in CACNB4A, whereas the Cacnb4 knockout mice showed severe neurological phenotype." (PMID 35813387, 2022). "Nuclear translocation of CACNB4 complexleads to transcription of several genes, including tyrosine hydroxylase, which is noteworthy due to its link to epilepsy." (PMID 32074998, 2020). "In two siblings with intellectual disability, psychomotor retardation, blindness, epilepsy, movement disorder and cerebellar atrophy we identified rare homozygous variants in the genes LTBP1, EMILIN1, CACNB4, MINAR1, DHX38 and MYO15 by whole-exome sequencing." (PMID 32176688, 2020). "CACNB4, CLCN2, MAGI2, and SRPX2 variants have all been proposed as causes of epilepsy." (PMID 40492992, 2025). "In a recent study, heterozygous CACNB4 mutations are not linked with epilepsy." (PMID 35813387, 2022). "Specifically, for both CACNB4 and GRIA splicing changes, it would be interesting to evaluate the relationship between SVRs and seizure frequency/severity in animal models of epilepsy to assess in vivo the consequences of the alterations." (PMID 17343748, 2007).
juvenile myoclonic epilepsy (8 papers, 2015 to 2023). "In humans, a mutation of CACNB4, leading to truncation of CACNB4 C-terminus, has been associated with juvenile myoclonic epilepsy." (PMID 32074998, 2020). "In humans, heterozygous variants in CACNB4 have been discovered in different phenotypes: The p.(R482*) nonsense mutation has been found in a case of juvenile myoclonic epilepsy; the p.(C104F) nonsense variant has been detected in patients with idiopathic generalized epilepsy and EA." (PMID 32443735, 2020). "Although data on specific gene in idiopathic generalized epilepsy is relatively scarce, mutations of voltage gated sodium channel subunit genes (CACNB4) and nonsense mutations in voltage gated calcium channels (CACNA1A) have been linked to idiopathic generalized epilepsy in two families." (PMID 25893123, 2015). "The calcium channel, voltage-dependent, beta-4 subunit (CACNB4) gene is associated with juvenile myoclonic epilepsy (JME)." (PMID 37637568, 2023). "CACNB4 could directly couple electrical activity to gene expression, which was responsible for a type of juvenile myoclonic epilepsy." (PMID 28388656, 2017).
episodic ataxia (6 papers, 2011 to 2023). "To date, the nonsense variant p.(Arg482*) and the missense variant p.(Cys104Phe) in CACNB4, both in the heterozygous state, have been reported in patients with JME and episodic ataxia, respectively." (PMID 32176688, 2020). "Genetic heterogeneity has been discussed to explain the absence of pathogenic CACNB4 variants in large cohorts of patients with episodic ataxia." (PMID 32176688, 2020). "Episodic ataxia (EA) is associated with SCA, and mutations in calcium channel genes may lead to EA; for example, mutations in CACNA1A and CACNB4 lead to EA2 (MIM: 108500) and EA5 (MIM: 613855), respectively." (PMID 31291898, 2019). "However, the lack of replication studies raises some doubts on whether the identified variants in CACNB4 have a major causal role in JME and/or episodic ataxia." (PMID 32176688, 2020). "Due to these nonepileptic events, molecular testing for episodic ataxia panel (CACNA1A, CACNB4, KCNA1, PNKD, PRRT2, SLAC1A3, VAMP1) was requested, and this came back normal." (PMID 37469362, 2023).
Ataxia (4 papers, 2012 to 2022). Ataxia refers to impaired coordination of voluntary muscle movement. "Episodic ataxia and JME are due to the heterozygous mutation in the form of missense variant p.Cys104Phe and nonsense variant p.Arg482* in CACNB4 leading to the disease and it was a rare mutation that was found non-Finnish European only in a single individual." (PMID 35813387, 2022). "EA is a clinically heterogeneous disorder characterized by recurrent spells of ataxia lasting minutes to hours which has been associated over time to a number of genes besides CACNA1A and KCNA1 (CACNB4, SLC1A3, FGF14, SLC2A1, ATP1A3, PRRT2) accounting for the majority of cases." (PMID 32823520, 2020).
alopecia (2 papers, 2013 to 2025). Hair loss usually from the scalp. "Specifically, CACNB4 was significantly associated with drug-induced grade 2 alopecia, whereas the other SNPs were suggestively associated with CIA." (PMID 40227705, 2025). "In summary, we identified strongly associated genetic variants near gene CACNB4 and several suggestively associated SNPs with chemotherapy-induced alopecia in breast cancer patients." (PMID 24025145, 2013). "SNP rs3820706 on CACNB4, which showed the strongest association with chemotherapy-induced alopecia with the genome-wide significance in the analysis of all-combined samples, showed modest associations in all of the subgroup analyses." (PMID 24025145, 2013). "We identified an SNP significantly associated with drug-induced grade 2 alopecia (rs3820706 in CACNB4 (calcium channel voltage-dependent subunit beta 4) on 2q23, P = 8.13 × 10-9, OR = 3.71) and detected several SNPs that showed some suggestive associations by subgroup analyses." (PMID 24025145, 2013).
breast carcinoma (2 papers, 2013 to 2025). "SNPs near genes such as CACNB4, STAM2, and ABCB1 are associated with a higher risk of CIA, particularly in breast cancer cohorts." (PMID 40227705, 2025).
Dystonia (2 papers, 2018 to 2023). An abnormally increased muscular tone that causes fixed abnormal postures. "In fact, virtually all genes associated with dystonia in spontaneous mutants (tottering, stargazer, ophisthotonus, ducky, lethargic, waddles, and wriggle) are involved in Purkinje cell Ca2+ signaling (Canca1a, Cacng2, Itpr1, Cacna2d2, Cacnb4, and Pmca2)." (PMID 29770609, 2018). "Similarly, individual AD9 has dystonia and seizures and a duplication encompassing three genes, CACNB4, SCN1A and SCN2A, each responsible for epilepsy syndromes with or without movement disorders." (PMID 36781956, 2023).
schizophrenia (2 papers, 2017 to 2018). A major psychotic disorder characterized by abnormalities in the perception or expression of reality. "Future studies should observe the effects of overexpressing CACNB4 in a model organism during adolescence, a period that is associated with schizophrenia onset as well as system-wide spine number changes in normative development." (PMID 29375326, 2017).
cardiomyopathy (1 paper, 2018). A disease of the heart muscle or myocardium proper. "There are eight genetic variants in the intronic region of the CACNB4 gene that we found to be associated with cardiomyopathy with p < 1 × 10−6." (PMID 29495422, 2018). "To assess whether any additional genetic variants at the CACNB4 locus were independently associated with cardiomyopathy, we performed a conditional analysis." (PMID 29495422, 2018).
channelopathy (1 paper, 2023). Channelopathies are a group of diseases caused by the dysfunction of ion channel subunits or their interacting proteins. "Genetic mutations in KCNA1, CACNA1A, CACNB4, SLC1A3, SCN8A, KCNMA1, and ATP1A3 genes that encode ion channels lend support to the channelopathy theory." (PMID 37008993, 2023).
depression (1 paper, 2017). "The depression etiology associated gene Cacnb4 is known as an important regulator of synapse density." (PMID 29375311, 2017).
episodic ataxia type 5 (1 paper, 2022). Episodic ataxia type 5 (EA5) is an extremely rare form of Hereditary episodic ataxia characterized by recurrent episodes of vertigo and ataxia lasting several hours. "Some reported mutations in the CACNB4 gene are linked with JME, IGE, and episodic ataxia, type 5." (PMID 35813387, 2022).
Intellectual disability (1 paper, 2020). "Here we report two patients, a 15-year-old boy and his 22-year-old sister, with severe intellectual disability, seizures, visual impairment, and dystonic and athetoid movements, carrying the homozygous CACNB4 missense variant c.377T>C/p.(Leu126Pro)." (PMID 32176688, 2020). "We report two siblings with severe intellectual disability lacking any language and motor development, seizures, visual impairment, and movement disorder who carry the homozygous p.(Leu126Pro) mutation in CACNB4 encoding the cytoplasmic β4 subunit of P/Q-type calcium channels." (PMID 32176688, 2020).
Parkinson disease (1 paper, 2014). A progressive degenerative disorder of the central nervous system characterized by loss of dopamine producing neurons in the substantia nigra and the presence of Lewy bodies in the substantia nigra and locus coeruleus. "We applied the neuro-ncRNA microarray to two mouse models with impaired voltage-gated calcium channel activity, i.e., to Cacnb4 mutant lethargic and CaV1.3 knockout mouse, implicated in various neurological disorders such as psychiatric disorders or Parkinson's disease." (PMID 25344396, 2014).
paroxysmal dyskinesia (1 paper, 2020). Paroxysmal dyskinesia (PD) is a rare heterogenous group of movement disorders manifesting as abnormal involuntary movements that recur episodically and last only a brief time. "Similarly, Cacnb4-deficient mice develop ataxic gait with intermittent attacks of motor dysfunction resembling paroxysmal dyskinesia, and in EEG recordings they display generalized cortical spike-wave discharges related to absence seizures." (PMID 32176688, 2020).
cancer (3 papers, 2022 to 2024). A tumor composed of atypical neoplastic, often pleomorphic cells that invade other tissues. "CACNB4 downregulates Wnt/β-catenin signalling, an important oncogenic signalling pathway that is associated with AML cancer stem cell phenotype." (PMID 39518047, 2024). "From the differential genes involved in these pathways, we identified several gene clusters uniquely upregulated in the CAFWPOI 4-5 type; neuronal development and function-related (RELN, MYH10, CACNB4, OXTR, CAV3, CHRM2) and inflammation and cancer-related (RELN, IL21R, EDNRB, CAV3, OXTR)." (PMID 36045118, 2022).
infection (3 papers, 2014 to 2024). The state of being infected such as from the introduction of a foreign agent such as serum, vaccine, antigenic substance or organism. "Increased expression of neuromotor-related genes such as Adam22, Cacnb4 and Zic1 (activated by NF1_LV infection) and ChAt (activated by NF45_LV infection) could explain PAM symptoms such as muscle weakness and seizures." (PMID 39735262, 2024).
neurological disorder (3 papers, 2014 to 2022). "In previous studies, it has been reported that the CACNB4 gene is associated with neurological disorders." (PMID 35813387, 2022). "The presence of the heterozygous c.1403G>A, p.Arg468Gln CACNB4 variant has been proposed to create more neurological disorders in those patients having a pathogenic SCN1A mutation where the current densities increased in calcium channel." (PMID 35813387, 2022). "The heterozygous CACNB4 variant c.1403G>A/p.(Arg468Gln) has been suggested to worsen the neurological disorder in a patient with a pathogenic SCN1A mutation by increasing calcium channel current densities." (PMID 32176688, 2020). "CACNB4 has previously been implicated in neurological disorders." (PMID 32176688, 2020). "Together, by a combination of in silico tools, animal model, clinical, and genetic data, we suggest that the homozygous p.(Leu126Pro) amino acid substitution in CACNB4 is the likely variant to underlie the patients’ neurological disease, although there is still a degree of uncertainty." (PMID 32176688, 2020). "Taken together, our study provides compelling evidence for the pathogenicity of the homozygous CACNB4 missense mutation p.(Leu126Pro) and identifies three potential pathomechanisms which, separately or in combination, likely underlie the severe neurological disorder in the affected siblings." (PMID 32176688, 2020).
tumor (2 papers, 2016 to 2018). "Five genes, CACNB4 (FCMSS 0.65), MAP3K6 (FCMSS 0.66), CD14 (FCMSS 0.66), CACNA2D4 (FCMSS 0.66), and MAP4K4 (FCMSS 1.52) had slightly stronger FC for MSS-specific tumors than for all tumor combined (FCoverall 0.67, 0.73, 0.68, 0.67, and 1.47, respectively)." (PMID 29636593, 2018).
cardiovascular disease (1 paper, 2021). "For example, the CACNB4 gene, associated with cardiovascular disease, would require a sample size equivalent to 370,000 individuals when using the additive test, 17 times larger than the required sample size under a recessive analysis." (PMID 33893285, 2021). "First, an intronic indel in the CACNB4 gene, rs201654520, associated with a nearly 20-fold increase in risk for cardiovascular disease (MAF = 0.017, OR [CI 95%] = 19.0 [5.5–65.8], p = 4.3 × 10−8)." (PMID 33893285, 2021).
neurodevelopmental disorder (1 paper, 2020). A behavioral and cognitive disorder with onset during the developmental period that involves impaired or aberrant development of intellectual, motor, or social functions. "Two siblings with a severe neurodevelopmental disorder carry the homozygous CACNB4 mutation causing an amino acid substitution known to disrupt the folding of the calcium channel β4 subunit." (PMID 32176688, 2020).
CACNB4 also shares sentences with these, for which no sentence is quoted: idiopathic generalized epilepsy (3 papers); Arthritis (2); movement disorder (2); psychiatric disease (2); absence seizures (1); alcohol dependence (1); Alzheimer disease (1); asthma (1); Blindness (1); Cerebellar atrophy (1); chronic myeloid leukemia (1); early infantile epileptic encephalopathy (1); epilepsy syndrome (1); episodic ataxia type 1 (1); gastric cancer (1); generalized tonic-clonic seizures (1); genetic disorders (1); glioblastoma (1); glioma (1); Hypertension (1); idiopathic dilated cardiomyopathy (1); macular degeneration (1); non-alcoholic fatty liver disease (1); prostate adenocarcinoma (1); retinitis pigmentosa (1); type 2 diabetes (1).